MALAT1 (metastasis associated lung adenocarcinoma transcript 1)
Diseases named in the same sentence as MALAT1 in open-access papers (continued):
Sharing a sentence is not in itself a finding about the gene and the disease.
cancer (continued). "It will be important to establish whether this reflects a species difference and whether clonal expansion follows insertions at MALAT1 e.g. in human-mouse cancer xenografts adventitiously infected in vivo by murine gamma-retroviruses." (PMID 27097319, 2016). "Accumulating evidences indicates that MALAT1 also promotes cancer progression by acting as a ceRNA." (PMID 27564100, 2016). "Previous studies showed that MALAT-1 promotes cancer progression, mainly through the regulation of gene expression, for example, the epithelial mesenchymal transition associated genes, ZEB1, ZEB2, and Slug and the apoptosis related genes, CASP3, CASP8, BAX, BCL2, and BCL2L1." (PMID 26989678, 2016). "Interestingly, a well-known oncogenic lncRNA, MALAT1, was the most common among 33 lncRNAs that were bound by miR-25 in all cancers." (PMID 27584791, 2016). "The pooled data revealed that increased MALAT1 expression was significantly associated with poor OS, DFS and RFS, indicating that MALAT1 has been shown to contribute to cancer progression and considered as a promising prog-nostic biomarker for cancer patients." (PMID 27777857, 2016). "Furthermore, MALAT1 regulates the expression of several cancer metastasis-related genes, but displays molecular subtype specific correlations with such genes." (PMID 27250026, 2016). "MALAT1 is involved in the formation of nuclear speckles, which are thought to be important for the processing of pre-mRNAs, and is further reported to be dysregulated in numerous cancers." (PMID 27686732, 2016). "For several cancers, MALAT1 expression is an independent prognostic parameter for survival." (PMID 26735578, 2016). "MALAT1 has been demonstrated to be a predictor of metastasis in a number of cancers including UBC." (PMID 26800519, 2016). "Metastasis-associated lung adenocarcinoma transcript 1 (MALAT1), a newly discovered long intergenic noncoding RNA (lincRNA), has been reported to be aberrantly expressed in various cancers, and may serve as a novel potential biomarker for cancer prognosis." (PMID 27777857, 2016). "MALAT1 is a lncRNA required for the EMT process of cancer cells." (PMID 27019196, 2016). "For example, malignant cancer cells are known to be more resistant to apoptosis, thus reduced apoptosis after exposure to anisomycin in reduced serum condition points towards the oncogenic potential and anti-apoptotic properties of MALAT1." (PMID 27250026, 2016). "We explored the correlation between the MALAT-1 lncRNA expression and cancer metastasis." (PMID 27586393, 2016). "Stable knockout of MALAT1 prevents cell proliferation and motility, which is associated with G2/M arrest, enhanced apoptosis, disrupted EMT, and weakened cancer stem-like properties in vitro, consistent with a putative oncogenic role for MALAT1 in this usually fatal disease." (PMID 27686732, 2016). "Malat1 may act as an oncogene in various types of cancer and has been reported as a competing endogenous RNA (ceRNA) that regulates ZEB2 expression by sponging miR-200s in clear cell kidney carcinoma." (PMID 27191262, 2016). "Notably, the lncRNA MALAT1, an oncogenic lncRNA that is overexpressed in various human cancers, was the most common lncRNA target of miR-25 in all cancers according to the analysis results." (PMID 27584791, 2016). "The levels of MALAT-1 expression in cancers could become an independent and novel promising candidate for predicting disease staging and prognostic for human cancer patients." (PMID 26989678, 2016). "Immunohistochemistry analysis showed that β-catenin expression was distributed in the membrane of cancer cells and significantly decreased in MALAT1-shRNA group compared with control group, and Ezh2 expression demonstrated the lower expression level in cell nucleus after MALAT1 knockdown." (PMID 27015363, 2016). "There is a bourgeoning literature on the role of MALAT1 over-expression in human cancer." (PMID 27097319, 2016).
cancer (continued). "MALAT1 is involved in metastasis through diverse mechanisms in various types of cancer." (PMID 26871474, 2016). "MALAT1 is up-regulated in several human cancers and promotes cancer cell proliferation." (PMID 27733185, 2016). "Therapeutic treatments that target MALAT1 can decrease cancer cell viability following transplantation and could be of clinical value." (PMID 26634812, 2016). "The lncRNA MALAT1 is upregulated in many cancers, including OS." (PMID 27458156, 2016). "Therefore, we conducted a systematic review and quantitative meta-analysis to further investigate the prognostic role of MALAT1 overexpression in human cancers." (PMID 27777857, 2016). "Therefore, a meta-analysis of 2094 cancer patients from 17 studies was undertaken to assess the prognostic value of MALAT1 expression in this study." (PMID 27777857, 2016). "Previous studies have suggested that MALAT1 might be associated with the PRC2 complex and promote cancer EMT." (PMID 26989421, 2016). "Furthermore, many other established, cancer-linked lncRNAs, including HOTAIR, MALAT-1, NEAT-1, and UCA-1, were found to be either extremely lowly expressed (mean and median cpm < 1) or insufficiently dysregulated in HNSCCs." (PMID 27323410, 2016). "MALAT1 is a lncRNA involved in regulation of cell motility and cancer metastasis." (PMID 26496443, 2015). "Moreover, the obvious oncogenic role of MALAT1 was demonstrated in a number of other cancer models, including bladder cancer, cervical cancer, uterine sarcoma, and osteosarcoma." (PMID 25954300, 2015). "This meta-analysis evaluated the prognostic role of MALAT1 in various cancers." (PMID 26420912, 2015). "MALAT1 is a prognostic marker for lung, gastrointestinal and several other cancers." (PMID 26082843, 2015). "Given this global pattern of deregulation in cancer, the biomarker potential of MALAT1 lies perhaps more in its prognostic rather than diagnostic application, correlating as it does with a poor outcome for patients with cancer." (PMID 26516918, 2015). "Immerging evidence has shown that MALAT1 contributes to cancer invasion and metastasis." (PMID 26522444, 2015). "Given Malat1’s well-established role in a broad range of human cancer cells and its newly identified role in the tumor microenvironment, i.e., in endothelial cells, raises the exciting question: Will Malat1 deletion impair tumor growth and progression in genetically engineered mouse models (GEMMs)?" (PMID 25580533, 2015). "MALAT1 has been shown to promote epithelial-to-mesenchymal transition and appears to regulate angiogenesis, further supporting its potential role during cancer progression." (PMID 26516918, 2015). "Examples of lncRNA genes having roles in lung tumorigenesis are H19, metastasis associated lung adenocarcinoma transcript 1 (MALAT1), smoke and cancer-associated lncRNA-1 (SCAL1), lncRNA-LET, intronic ncRNA AK126698, BC-200 and hox transcript antisense intergenic RNA (HOTAIR)." (PMID 25884481, 2015). "Therefore, we performed a systematic review and quantitative meta-analysis to assess the prognostic role of MALAT1 expression in various cancers." (PMID 26420912, 2015). "Therefore, expression of Malat1 correlates with tumor development, progression, metastasis and survival in different cancer types." (PMID 26335021, 2015). "Malat1 is one of the most significant molecules of long non-coding RNA (lncRNA), which is commonly up regulated in malignant cells, hence it is usually considered as a biomarker of some type of cancers." (PMID 26335021, 2015). "Malfunction of MALAT1 affects cancer cells' mobility, invasiveness, and survival through the abnormal splicing of genes that are involved in oncogenesis- and metastasis-related procedures (e.g., WNT and MAPK signaling, cytoskeletal organization and cell cycle, EMT)." (PMID 26064090, 2015).
cancer (continued). "Due to recent results indicating aberrant splicing patterns in various cancer types, it may well prove that MALAT1 dysregulation is partially responsible for this observation." (PMID 25101115, 2014). "MALAT1 regulates the cell cycle by modulating key transcription factors which, when deregulated, could promote cancer progression." (PMID 25400658, 2014). "MALAT1 is also thought to tether and titre SR proteins in cancer cells." (PMID 25437750, 2014). "It is interesting to note that the aberrant expression of MALAT1 has also been observed in several cancers; whether such altered expression is a cause or an effect of carcinogenesis needs to be determined." (PMID 23555285, 2013). "Differences of normalized MALAT1 levels between cancer patients and cancer-free subjects were significant for NSCLC vs. controls (p < 0.0001), AdCa vs. controls (p = 0.0043), and SqCC vs. controls (p = 0.0001), whereas the difference between AdCa and SqCC was not significant." (PMID 24313945, 2013). "By leveraging advanced delivery systems and exploring mechanisms like epigenetic regulation (e.g., HDAC inhibition and MALAT1 targeting), polyphenols may redefine cancer treatment as low-toxicity, multitarget agents capable of overcoming drug resistance and improving patient outcomes." (PMID 41596402, 2026). "Targeting MALAT1 may reduce metastatic behavior; serves as a marker for invasive cancer types." (PMID 40959208, 2025). "PathwaysKnockdown of lncRNA MALAT1 has been reported to affect transcription and/or pre-mRNA splicing of key genes involved in migration and cell adhesion, as well as genes involved in cancer pathways related to invasion, metastasis, and chemotherapy resistance." (PMID 39319867, 2025). "While further studies utilizing advanced and physiologically relevant in vivo models that replicate certain types of cancer are necessary, the current evidence suggests that MALAT1 may hold promise as a primary candidate for future clinically applicable lncRNA-based therapies against MI." (PMID 39171328, 2024). "For example, LincRNA-p21\GAS5\MALAT1, which are located in the cytoplasm and act as competing endogenous (ceRNAs) or interact with RBPs, could enhance mRNA stabilization and translation in the context of cancer progression." (PMID 38041756, 2024). "Furthermore, ASOs have been used to study and to target the MALAT1 lncRNA in various cancer types." (PMID 38338910, 2024). "Moreover, MALAT1 is known to be misregulated in many human cancers." (PMID 38674413, 2024). "In addition, MALAT1 also modulates its suppressive effect by negatively modulating Myeloid-derived suppressor cells (MDSCs) and decreasing peripheral blood mononuclear cells (PBMCs) in cancer patients." (PMID 38201661, 2024). "Moreover, the type of cancer or the unique combination of genetic changes may provide different explanations of the impact of MALAT1 expression on cell cycle changes." (PMID 38674413, 2024). "Additionally, ELAC2 exhibits non-tRNA target cleavage, exemplified by its processing of MALAT1, a long noncoding RNA implicated in many cancers." (PMID 38826313, 2024). "Many studies have focused on examining the impacts of the expression levels of specific genes, including MALAT1, on the regulation of the cell cycle, mainly in the process of carcinogenesis, which involves uncontrolled proliferation and inhibition of the apoptosis of cancer cells." (PMID 38674413, 2024). "However, a meta-analysis, drawing from both literature and the Gene Expression Omnibus (GEO) database, suggests that the lncRNA MALAT1 could serve as a novel biomarker, not only for various cancers but also for MetS-related diseases." (PMID 39502508, 2024). "The exact mechanism of how MALAT1 helps in cancer development and progression is unknown." (PMID 38328782, 2024).
cancer (continued). "Notably, the specific miRNAs with which MALAT1 interacts differ from those identified in solid tumors, indicating a complex and varied regulatory landscape that warrants further investigation in the context of different cancer types." (PMID 39335515, 2024). "Furthermore, it was shown, that MALAT1 may act as master regulator of several protein-coding hub-genes in drug-resistant NRAS-mutant cancer." (PMID 37235843, 2023). "Therefore, MALAT1 can impact sensitivity to radiation therapy in cancer." (PMID 37370745, 2023). "In addition, MALAT1 may affect cancer carcinogenesis by activating the Wnt/-catenin, ERK/MAPK, and PI3K/AKT pathways, while concomitant activation of oncogenic pathways may cause strong carcinogenic effects." (PMID 37244966, 2023). "Moreover, they found that MALAT1 was upregulated in radioresistant cancer cell lines, and down-regulation of MALAT1 could inhibit cell proliferation and metastasis through the apoptosis pathway." (PMID 35978049, 2023). "Additionally, MALAT1 can interact with microRNA and cancer drugs." (PMID 38045858, 2023). "Therefore, MALAT1 can also induce drug resistance of cancer cells by promoting the EMT." (PMID 36829256, 2023). "Moreover, MALAT1 has been found to be a potential therapeutic target for cancer." (PMID 36829256, 2023). "Likewise, up-regulation of lncRNA HOTAIR and MALAT1, down-regulation of lncRNA Meg3 and dual function of lnRNA H19 were seen in different cancer types, including lung cancer, ovarian cancer, prostate cancer, breast cancer, colorectal cancer, gastric cancer, and liver cancer." (PMID 37568568, 2023). "Finally, and of particular importance for further consideration, increased levels of MALAT1 in cancer cells may contribute to their resistance to 5FU chemotherapy." (PMID 35922756, 2022). "In addition, MALAT1 can promote cancer development by suppressing cell apoptosis." (PMID 35300579, 2022). "Thus, MALAT1 promotes the progression, invasion and metastasis of cancer to a certain extent." (PMID 35208500, 2022). "Both MALAT1 down-regulation and miR-20b-5p up-regulation could attenuate microsphere formation and self-renewal ability, decrease the proportion of cancer stem cells, and down-regulate levels of stemness-related proteins and those regulating cellular metabolism." (PMID 36582800, 2022). "Besides, H19 and MALAT1 were upregulated in HPV+ cancers than those in HPV− cancers, which indicated that HPV might participate in the regulation of the ceRNA network." (PMID 36158885, 2022). "LncRNAs may serve as biomarkers of cancer, such as nuclear enriched abundant transcript 1 (NEAT1), HOX Transcript Antisense RNA (HOTAIR), metastasis-associated lung adenocarcinoma transcript 1 (MALAT-1), H19." (PMID 36034367, 2022). "This suggests that MALAT1 may be an important target for cancer therapy." (PMID 36419933, 2022). "Interestingly, the transcriptional regulator YAP1 may be significantly involved in the upregulation of MALAT1 gene expression in cancer cells." (PMID 35922756, 2022). "Latest studies revealed that MALAT1 exerted an essential impact on the regulation of many pathophysiological processes such as neurologic disorders, vascular diseases, and cancers by affecting the proliferation, migration, apoptosis and invasion of cancer cells." (PMID 35228564, 2022). "In metastatic bladder cancer, MALAT1 directly interacts with suz12 (a component of histone-modifying complex-PRC2) to regulate the expression of EMT-associated genes (E-/N-cadherin, fibronectin, MMP9), contributing to the migration and metastasis of cancer cells in vitro and in vivo." (PMID 35736633, 2022).
cancer (continued). "Thus, investigating whether MALAT1 can influence cancer progression through its regulation of EZH2 warrants further research." (PMID 36419933, 2022). "Therefore, MALAT1 can be a potent gene for cancer prediction and diagnosis." (PMID 35305641, 2022). "The H1.hESC and GM12878 cell lines had cytoplasmic-to-nuclear (CN) RCI of 28.2% and 10.3%, respectively, showing that MALAT1 is actively expressed in embryonic cells and B lymphocytes, and therefore might play a role in cancer cell proliferation, differentiation, migration, and humoral immunity." (PMID 36419933, 2022). "Therefore, quercetin can prevent the growth and development of cancer by inhibiting MALAT1." (PMID 33805687, 2021). "However, we have identified the possible structural differences between MALAT1 in different cellular contexts that could exacerbate K562 and HeLa cells, leading to mechanistic insights regarding the complex cancer-specific functions of MALAT1." (PMID 33450947, 2021). "Moreover, several lncRNAs that have been previously reported to be involved in various cancers as PVT1, HOTAIR, NEAT1, and MALAT1 may contribute to cancer development and progression." (PMID 33670447, 2021). "Moreover, m6A changes in MALAT1 alter its binding capacity of miRNAs involved in cancer." (PMID 33430133, 2021). "However, its parent RNA, MALAT1, is partially upregulated in some cancer cell lines, which might attribute to the limited cancer cells." (PMID 34001866, 2021). "Furthermore, evidence of suppressed in vitro cell proliferation, migration, and invasion, in addition to repressed cell growth in vivo, indicate a central role of MALAT1 in the promotion of cancer cell migration and disease progression through miR-429 sponging." (PMID 35011635, 2021). "In fact, since the discovery of MALAT1 (Metastasis-associated lung adenocarcinoma transcript 1) in the early 2000s, dysregulation of more than a dozen other lncRNAs, such as H19, XIST, and HOTAIR have steadily been found to be associated with cancer progression and drug resistance." (PMID 33803328, 2021). "Given that MALAT1 plays a role in key cellular processes (such as alternative splicing and transcriptional regulation) and its expression is altered in several cancer types, further investigations may reveal the role of m6A modification of MALAT1 in cancer cells." (PMID 33564819, 2021). "Interestingly, small molecules specifically targeting the MALAT1 triple helix structure have been identified, and they could represent novel strategies for the treatment of MALAT1-driven cancer and investigate its functions." (PMID 34206504, 2021). "In addition, lncRNA MALAT1 was suggested for application as a treatment strategy related to cancer." (PMID 34756133, 2021). "While MALAT1 has been shown to promote cancer cell migration, invasion and metastasis in a variety of cancer types, MALAT1 is expressed at higher levels in human RCC tissues than normal tissues, and higher levels of MALAT1 expression in human RCC tissues are associated with poorer patient prognosis." (PMID 33593347, 2021). "MALAT1 is one of the most studied lncRNAs in cancer and has several oncogenic functions as modulates multiple signaling pathways involved in the enhancement of cell proliferation, metastasis, and invasion that commonly results in poor prognosis in cancer patients." (PMID 34575316, 2021). "A large number of previous studies demonstrated that the abnormal expression of MALAT1 is related to tumor proliferation and metastasis, indicating that the increased expression of MALAT1 may be a valuable predictive biomarker for the poor prognosis of different types of cancer." (PMID 34761116, 2021). "However, the role of MALAT1 in cancer metastasis is not yet fully understood." (PMID 33435206, 2021). "It would be reasonable to hypothesis that MALAT1 is a potential target for cancer therapy." (PMID 34164906, 2021).